TLR4 (toll like receptor 4)
Diseases named in the same sentence as TLR4 in open-access papers (continued):
Sharing a sentence is not in itself a finding about the gene and the disease.
atherosclerosis (continued). "It was found that 95% pure P. cocos polysaccharide (PCP) intervened in atherosclerosis induced by a high-fat diet by inhibiting the activation of the TLR4/NF-κB pathway in the aorta and lowering inflammatory factors and lipid levels." (PMID 40141970, 2025). "LPS from gut bacteria activates the immune system, triggering inflammation through TLR4 signaling, leading to vascular dysfunction, increased platelet aggregation, and atherosclerosis." (PMID 40421334, 2025). "This alteration subsequently affects toll‐like receptor 4 (TLR4) signaling, promoting NF‐κB‐mediated proinflammatory gene expression, which contributes to vascular inflammation and the progression of atherosclerosis." (PMID 41020041, 2025). "LPS induces systemic inflammation via TLR4/NF-κB and endothelial dysfunction, mechanistically linking it to atherosclerosis." (PMID 40943409, 2025). "PCSK9 has also been shown to activate TLR4 signaling pathways, linking it directly to innate immune responses and atherosclerosis." (PMID 40868936, 2025). "TLR4 activates the expression of several pro-inflammatory cytokine genes that play key roles in myocardial inflammation, particularly myocarditis, atherosclerosis, myocardial infarction, ischemia-reperfusion injury, and heart failure." (PMID 40809170, 2025). "Oxidized LDL, common in atherosclerosis, activates macrophage TLR4, triggering NF-κB and inflammasome signaling, while self-RNA can engage TLR7/8, contributing to chronic inflammation and autoimmunity in the elderly." (PMID 41373468, 2025). "In atherosclerosis, LPS-mediated TLR4 activation on vascular macrophages induces localized inflammation, promoting plaque formation." (PMID 40943978, 2025). "Dysregulated TLR signaling contributes significantly to the development of atherosclerosis, specifically with the expression of TLR4 detected in ECs and MØ, as well as VSMCs of both human and mouse atherosclerotic lesions." (PMID 41155497, 2025). "Disruption of these domains can alter the localization and function of the signaling complex toll-like receptor 4 (TLR4), a key mediator of macrophage-driven inflammatory responses in atherosclerosis." (PMID 40564102, 2025). "Animal studies have shown that sinigrin suppresses oxidative stress in cerebral ischemia–reperfusion injury by inhibiting the TLR4/MyD88 signaling pathway, which in turn helps prevent or slow the progression of atherosclerosis." (PMID 40634132, 2025). "Paeoniflorin alleviates the pathological process of atherosclerosis by inhibiting TLR4 and its downstream signaling pathways, thereby mitigating the inflammatory response." (PMID 40242436, 2025). "LPS triggers systemic inflammation through Toll-like receptor 4 (TLR4) activation, contributing to endothelial dysfunction and atherosclerosis." (PMID 39497887, 2024). "Plasma LPS exacerbates atherosclerosis through the activation of the Toll-like receptor 4 signalling pathway in a dose-dependent manner." (PMID 38243314, 2024). "The potential role of TLRs, including TLR2 and TLR4, in the pathogenesis of atherosclerosis and inflammatory effects of Ox-LDL has been reported." (PMID 39404395, 2024). "Overall, HMGB1 plays a significant role in the formation of atherosclerosis, potentially mediating inflammation and cell necrosis through the TLR4 signaling pathway." (PMID 38493291, 2024). "Undoubtedly, the pro-inflammatory signaling of monocytes/macrophages through toll-like receptors, such as toll-like-receptor-4 (TLR4), triggered by bacterial endotoxins like LPS, has been implicated in the pathogenesis of atherosclerosis." (PMID 38410507, 2024).
atherosclerosis (continued). "Lectin-like oxidized low-density lipoprotein-1 (LOX-1), an integral membrane glycoprotein with widespread expression on the ECs, is involved in atherosclerosis and has some common pathways with TLR4 in atherosclerotic lesions." (PMID 38445291, 2024). "In line with this, TLR4 deficiency protects rodents against FFA-induced inflammation and atherosclerosis upon feeding of a high SFA diet." (PMID 39493874, 2024). "Several researches have indicated Corilagin’s potential in preventing and treating atherosclerosis, and find Corilagin probably mitigate atherosclerosis by inhibiting the TLR4 signaling pathway." (PMID 38803504, 2024). "According to previous findings, Corilagin can inhibit NLRP3 inflammasome activation and pyroptosis in ischemia-reperfusion induced intestinal and lung injury, and ameliorate atherosclerosis by restraining the TLR4 signaling pathway." (PMID 38803504, 2024). "One critical factor in the initiation and progression of atherosclerosis is the release of inflammatory factors and cytokines produced by the MyD88 upon the activation of toll-like receptor 4 (TLR4)." (PMID 39247623, 2024). "There is substantial evidence that the gut microbiota, which includes Escherichia coli (EC) and its lipopolysaccharide, can impact the development of atherosclerosis through Toll-like receptor 4 (TLR-4)—induced cellular oxidative stress." (PMID 38459219, 2024). "In sum, these results suggested that oxLDL enhanced the interaction between CD36 and TLR4 in ECs and further triggered NF-κB signal transduction, which was related to the effect of Ash2l in promoting atherosclerosis." (PMID 38280036, 2024). "An increase in the absolute number of TLR4-positive intermediate monocytes (CD14++CD16+TLR4+) was also found in patients with polyvascular atherosclerosis progression—479.0 cells/μL (388.0–543.0) versus 761.0 cells/μL (273.2–466.5), p = 0.0099." (PMID 37569579, 2023). "The expression levels of TLR4 mRNA and protein were found to be elevated in mononuclear cells of patients with coronary artery disease, acute myocardial ischemia, atherosclerosis, acute myocardial infarction, heart failure, and dilated cardiomyopathy." (PMID 37239362, 2023). "A follow-up study demonstrated that these anti-atherosclerosis effects of octanoate were attributable to modulation of the TLR4/NFkB pathway." (PMID 37463952, 2023). "In vitro studies have shown that miR-218-5p regulates apoptosis and inflammation of macrophage-derived foam cells by targeting TLR4, thus promoting the progression of atherosclerosis." (PMID 36890438, 2023). "Due to its involvement in innate immunity and inflammation, TLR4 has been described as a crucial mediator of atherosclerosis." (PMID 37830572, 2023). "The discovery of the importance of TLR-4 in the pathogenesis of atherosclerosis prompted research on the role of infections and the gut microbiota in this disease." (PMID 38139349, 2023). "Signalling through TLR4 contributes to vascular inflammatory pathologies such as atherosclerosis and hypertension." (PMID 36937865, 2023). "The assessment of TLR4-positive monocytes significantly improved the prognostic model for the progression of lower limb arterial atherosclerosis (C-index 0.728 (0.642–0.815) versus 0.637 (0.539–0.735); p = 0.038)." (PMID 37569579, 2023). "At the same time, according to the available data, for the first time we have established the prognostic significance of TLR4-positive intermediate monocytes in relation to the short-term progression of polyvascular atherosclerosis." (PMID 37569579, 2023). "The expression of TLR2 and TLR4 at the wall of the blood vessel can enhance atherosclerosis in a synergistic way." (PMID 37520489, 2023). "An increase in the number of circulating TLR4-positive intermediate monocytes was an independent predictor of the short-term progression of lower limb artery and polyvascular atherosclerosis." (PMID 37569579, 2023).
atherosclerosis (continued). "Elevated LPS enters the circulation and binds to TLR4, which in turn stimulates the TLR4/NF-κB signaling pathway, thereby activating various inflammatory factors and potentially resulting in atherosclerosis." (PMID 38041095, 2023). "Our previous results suggest that C8:0 can inhibit inflammation and improve atherosclerosis through the TLR4/NF-κBp65 signaling pathway in apoE−/− mice." (PMID 36904298, 2023). "This review suggests that TMP inhibits inflammation in atherosclerosis by modulating TLR4, IL-6, and IL-1β levels." (PMID 35500001, 2022). "Previous studies have shown that atherosclerotic arteries express TLRs, and the activation of TLRs, specially TLR2 and TLR4, has a certain influence on atherosclerosis." (PMID 36219347, 2022). "Previous studies have shown that PM2.5 promotes plaque vulnerability at different stages of atherosclerosis, the formation of foam cells, and lung injury and exacerbates allergic inflammation in the murine lung via the TLR4/MyD88/NFκB pathway." (PMID 35795853, 2022). "TLR4 signaling is a multi-target anti-inflammatory pathway, and it plays a crucial role in occurrence and development in inflammation and atherosclerosis." (PMID 36313296, 2022). "Polydatin synergizes with P. sibiricum polysaccharides in preventing the development of atherosclerosis in ApoE–/– mice by inhibiting the TLR4/MyD88/NF-κB signaling pathway." (PMID 35845572, 2022). "Toll-like receptor (TLR) 2 and TLR4 are microbial sensors and promotors for atherosclerosis, leading to atheroma development and progression, and the development of cardiovascular disease." (PMID 35872802, 2022). "Meanwhile, restoration of miR-182-5p was also reported to reduce atherosclerosis-induced oxidative stress and apoptosis by means of downregulating TLR4 and restraining ROS production." (PMID 35422485, 2022). "FN-EDA and TLR4 double knockout mice were found to be protected against plaque development and atherosclerosis progression." (PMID 35690624, 2022). "TLR4 accelerates the progression of atherosclerosis and increases the expression of ICAM-1 and VCAM-1, leading to the synergistic activation of NF-κB in vascular walls in vivo and vascular smooth muscle cells in vitro." (PMID 35734399, 2022). "Previous studies have shown that TLR4 plays a vital role in the pathogenesis of intimal hyperplasia, atherosclerosis, and hypertension." (PMID 35845572, 2022). "In particular, TLR4 activation in macrophages in atherosclerosis can be linked to DAMP (e.g., the stress protein S100), and TLR4 can form functional membrane clusters with SRs: SR-J1 (RAGE) and SR-B2 (CD36)." (PMID 35562986, 2022). "Statins through inhibition of TLR4 expression and regulation of the TLR4/Myd88/NF-κB signaling pathway can slow the progression of atherosclerosis." (PMID 35571155, 2022). "Although the potential role of TLR4 in the early stages of atherogenesis remains a subject for study, it is known that the low expression of TLR4 in endothelial cells of normal arteries is markedly increased in atherosclerosis." (PMID 35163232, 2022). "In summary, in macrophages, LPCAT3 exerts a proinflammatory effect by regulating the expression of C-SRC and TLR4, thereby promoting the further development of atherosclerosis." (PMID 35711841, 2022). "Accumulating evidence from basic research shows that PCSK9 promotes vascular inflammation through upregulating classical pro-inflammatory pathways involved in atherosclerosis, such as TLR4/MyD88/NF-κB and NLRP3 inflammasomes." (PMID 36291690, 2022). "The expression of TLR2 and TLR4 at the blood vessel wall can enhance atherosclerosis in a synergistic way." (PMID 35928361, 2022). "Immunohistochemical staining of TLR4 showed that in the atherosclerosis model group, the TLR4-positive regions in the Bif." (PMID 34681423, 2021).
atherosclerosis (continued). "In other studies, it has been shown that atorvastatin has an anti-inflammatory effect on atherosclerosis through TLR4 and the MYD88-dependent pathway in a dose- and time-dependent manner." (PMID 32378144, 2021). "High FFA contribute to the development of atherosclerosis, are proinflammatory and activate TLR4 signaling cascades." (PMID 34834808, 2021). "TLR9 appears to play a protective role in the progression of atherosclerosis, while TLR4 can either protect or accelerate plaque burden." (PMID 33572939, 2021). "Given that LDL cholesterol is the main harmful lipid that accelerates vascular endothelial damage and atherosclerosis, these results suggested that TLR4 is important for age-related vascular injury." (PMID 34740366, 2021). "Exaggerated TLR4 signaling is implicated in the progression of numerous pathological CVD states, including hypertension, atherosclerosis and heart failure." (PMID 34042301, 2021). "The endotoxin LPS can interact with TLR4 to trigger a cytokine cascade, leading to the development of atherosclerosis." (PMID 34948275, 2021). "Quercetin, which is a green tea flavonoid, inhibited the expression of TLR2 and TLR4 and nuclear translocation of the NF-κB p65 subunit in atherosclerosis rats." (PMID 34943034, 2021). "Further evidence supporting the roles of TLR2 and TLR4 in atherosclerosis is the fact that TLR2 and TLR4 agonists can stimulate atherosclerosis in various mouse models." (PMID 32378144, 2021). "They observed that atherosclerosis was decreased in a TLR4 knockout hypercholesterolemic mouse model." (PMID 32378144, 2021). "In fact, mouse models have shown the importance of TLR4, a receptor for LPS, and its signaling in diet-induced insulin resistance and atherosclerosis." (PMID 34299233, 2021). "Our results are consistent with a study in which inhibiting TLR4 alleviated pathological vascular injury during atherosclerosis." (PMID 34740366, 2021). "It is well-established that the signaling cascade initiated by the innate immune arm involving Toll-like receptor 4 (TLR4) is activated during inflammatory responses and is considered to be closely related to atherosclerosis." (PMID 35185540, 2021). "SIS can possibly increase the risk of atherosclerosis through inducing abnormal HPA-axis activity and subsequently lead to TLR4 up-regulation, vascular inflammation, high M1/M2 ratio in intima." (PMID 34580342, 2021). "TLR4 is required for Ox-LDL-induced differentiation of macrophages into foam cells in the early stages of atherosclerosis." (PMID 33456670, 2020). "We clarified the anti-atherosclerosis efficacy of corilagin on monocytes/macrophages by inhibiting the TLR4 signaling pathway and then suppressing the inflammatory response in vitro and in vivo." (PMID 32849545, 2020). "Other studies have demonstrated that TLR4 gene silencing reduces the levels of MMP-9 in human aortic smooth muscle cells in the context of atherosclerosis." (PMID 32784904, 2020). "Frank and his colleagues reported that P. gingivalis demands TLR2 to induce oral inflammatory bone loss in mice, and P. gingivalis infection promotes atherosclerosis in hyperlipidemia mice with increased expression of TLR2 and TLR4." (PMID 32002588, 2020). "TLR4/NF-κB signaling pathway is involved in the regulation of PCSK9 on atherosclerosis inflammation." (PMID 31957804, 2020). "In hyperlipidemia, pyroptosis in endothelial cells (ECs) induces atherosclerosis via the toll-like receptor 4 (TLR4) pathway." (PMID 33339328, 2020). "More and more studies have shown that TLR4 was one of the important factors leading to the inflammatory process of atherosclerosis, intimal hyperplasia and accelerated formation of atherosclerotic plaque." (PMID 32122353, 2020).
atherosclerosis (continued). "Maitra and his colleagues confirmed high dose LPS can significantly increase the expression of NF-κB, and low dose LPS can induce macrophage inflammation and promote the occurrence of atherosclerosis through TLR4 and IRAK1." (PMID 32002588, 2020). "What's more, TLR4 plays a major role in myocardial inflammation, including MI, myocardial I/R injury, myocarditis, aortic valve diseases, hypertension, atherosclerosis and HF." (PMID 32757377, 2020). "In animal studies, TLR4 activity inhibition has also been demonstrated to reduce the levels of atherosclerosis and myocardial inflammation." (PMID 32397494, 2020). "Toll-like receptor 4 (TLR4), a typical representative of pattern recognition receptors in innate immune responses, plays an important role in activation of inflammation in atherosclerosis." (PMID 32028672, 2020). "In this study, we used the Ana-1 cell line, primary abdominal macrophages of mice, and a PAD model in rats to explore the effect of corilagin on amelioration of atherosclerosis development via the TLR4 signaling pathway." (PMID 32849545, 2020). "The inflammatory responses mediated by TLR4 play important roles in the initiation and progression of atherosclerosis." (PMID 31182969, 2019). "Other studies showed that TLR2 expression is increased in patients with diabetes, and TLR2/TLR4 stimulation induces an enhanced inflammation in obese patients with atherosclerosis." (PMID 31582899, 2019). "Based on this, we tended to further investigate the effect of HMGB1/TLR4 signaling on the development of atherosclerosis induced by CUMS." (PMID 30881312, 2019). "The expression levels of TLR1, TLR2, and TLR4 were found elevated in human and experimental models of atherosclerosis." (PMID 31565149, 2019). "In our previous study, TLR4 signaling was involved in the development of atherosclerosis in a murine model." (PMID 31023999, 2019). "HSP60 stimulates the host macrophages during processes such as atherosclerosis, and is mostly involved in the TLR4 pathway, although it can also play a role in the TLR2 pathway." (PMID 31086403, 2019). "Our study demonstrates that HMGB1 promotes CUMS-induced atherosclerosis via activating TLR4 signaling, which drownregulates the expression of PPARγ-LXRα-ABCA1." (PMID 30881312, 2019). "TLR-4 signaling is not only important in starting the inflammation responses, but also plays a role in pathogenesis development of atherosclerosis." (PMID 31011554, 2019). "Recent studies have demonstrated a critical role for TLR4 in the initiation and progression of inflammation in atherosclerosis." (PMID 31583048, 2019). "MiR-590 increases endothelial cell apoptosis by inactivating TLR4/NF-κB signaling in atherosclerosis." (PMID 31949464, 2019). "The endotoxin can bind to TLR4/MD2 complexes, which cause subsequent inflammation, and has been implicated in the development and progression of atherosclerosis and subsequent coronary artery disease and HF." (PMID 29576748, 2018). "Toll-like receptor 4 signaling in atherosclerosis plays an important role in activation of inflammation in activation of inflammation and lipid accumulation, which are all associated with atherosclerosis plaque progression and vulnerability." (PMID 30142970, 2018). "Pro-inflammatory cytokines Interferon (IFN)α, IFNγ and Toll-like receptor 4 (TLR4) activators are key factors contributing to early stages of atherosclerosis." (PMID 30283459, 2018). "TLR4 plays a critical role in myocardial inflammation, including myocarditis, MI, myocardial I/R injury, HF, aortic valve diseases, atherosclerosis, and hypertension." (PMID 29576748, 2018). "Atherosclerosis-mediated inflammatory response promoted the expression of inflammatory receptor TLR4 and inflammatory signaling NF-κB significantly (P < 0.01)." (PMID 29619063, 2018). "Various drugs exert anti-atherosclerosis effects, such as statins and thiazolidinediones, via targeting TLR4." (PMID 29896109, 2018).